ELN (elastin)
Diseases named in the same sentence as ELN in open-access papers (continued):
Sharing a sentence is not in itself a finding about the gene and the disease.
tumor (continued). "The ECM is altered during tumor progression as a result of ECM deposition by matrix metalloproteinases or mechanical stress resulting from tumor growth, whereas the interstitial matrix is predominantly composed of substances such as collagens I and III, fibronectin (FN), and elastin." (PMID 36403050, 2022). "By contrast, MITF, CCR7, JAK1, ELN, and SLC6A4 were lowly expressed in tumor tissues." (PMID 36425071, 2022). "Although the signal mediation of the receptor in tumor cells is not yet fully elucidated, a different extensive binding of tumor cell lines to elastin has been observed in Lewis lung carcinoma cells." (PMID 34827210, 2021). "Elastin is an essential component of the ECM and constantly changes during tumor development." (PMID 34827210, 2021). "ELN is a key component of the ECM family and plays critical roles in elasticity properties in soft tissues and may contribute to tumor formation." (PMID 32171282, 2020). "Therefore, a potential mechanism is that ELN induces the EMT process in colon tissues and increases tumor cell proliferation and invasion." (PMID 32171282, 2020). "While the mechanisms of ELN induced cancer cell migration remain unclear, EMT is an important process in tumor development and many ECM proteins have been identified to induce EMT." (PMID 32171282, 2020). "LOXL2 is a member of the lysyl oxidase gene family which catalyzes the crosslinking of extracellular collagen and elastin resulting in increased ECM stiffness and subsequent activation of the kinases FAK and SRC, which enable tumor cells to proliferate and invade." (PMID 30473751, 2018). "For TPEF, however, the non-tumorous tissue sections arise from dermal tissue next to tumor nests, which contains no elastin." (PMID 27429131, 2013). "It was suggested that partial preservation of elastic fibres in the tumour depth was a relatively good predictive factor, whereas complete absence of elastin was an adverse one." (PMID 20959825, 2010). "As the copper-dependent LOX family of proteins plays a crucial role in catalyzing the cross-linking of collagen and elastin, which enhances cell migration and facilitates tumor progression, the ATOX1-ATP7A-LOX cascade is expected to contribute to ECM remodeling in the tumor microenvironment." (PMID 40721800, 2025). "These probes enhance our understanding of tumor biology, facilitate early cancer detection, enable non-invasive monitoring of tumor progression, and have potential applications in theranostics for precision oncology through targeting elastin." (PMID 39770505, 2024). "Similarly, we have shown in a recent study by our group that implementing routine elastin staining on all tumor-containing blocks, rather than on selected tumor-containing blocks, increased the venous invasion detection rate in CRC." (PMID 37894944, 2023). "ECM, the crucial noncellular component of the TME, primarily composed of collagen, non-collagen, elastin, and proteoglycan, could promote tumor growth and progression through transmitting signals secreted from fibroblasts and epithelial cells within TME." (PMID 36159996, 2022). "The role of ELN in tumor development and metastasis has not been fully understood." (PMID 32171282, 2020). "Dysregulation of MMP gene expression and protein levels may not be able to explain the increased ELN level in tumor tissues from CRC patients." (PMID 32171282, 2020). "This “chemoresistance” was partially based on tumor-protective effects by enhanced CA-MSC-mediated filament expression including collagen, laminin, elastin, and fibronectin which may explain similar effects in the filamentous tumor microenvironment of MSC co-cultured SK-OV-3 cells." (PMID 30316300, 2018).
tumor (continued). "Elastin is degraded by MME, which might facilitate tumor and/or stroma cell invasion." (PMID 24460801, 2014). "Elastin and MMP-9 expression are upregulated in colorectal cancer tumor tissues and cancerous epithelial cells as opposed to healthy tissues and cells from the same donor." (PMID 37001705, 2023). "During tumor development and progression, the complex ECM network is established by fibrillar or non-fibrillar collagens, elastin, proteoglycans, glycoproteins, laminins, fibronectins and other matrix proteins." (PMID 35331296, 2022). "The non-cellular compartment of the tumor stroma comprises extracellular matrix (ECM) components like collagens, laminins, fibrinogen, elastin, and proteoglycan, and secreted factors such as cytokines, chemokines, and sequestered growth factors." (PMID 33050580, 2020). "In this study, we analyzed ELN gene expression in tumors from CRC patients and adjacent non-tumor colon tissues and healthy controls from two existing microarray datasets." (PMID 32171282, 2020). "We have also demonstrated that an elastin nonapeptide of consensus sequence xGxPGxGxG, AGVPGLGVG (AG-9), favors the migration and invasion of tumor cells through MMP-2 and uPA increases." (PMID 33396696, 2020). "ELN mRNA expression is increased in tumors from CRC patients compared to normal colon tissues from healthy controls, and in tumor tissue compared to adjacent non-tumor colon tissues from the same CRC patients." (PMID 32171282, 2020). "We aimed to measure ELN gene expression and its related MMP9, MMP12 and TIMP3 gene levels in tumor from CRC patients compared to adjacent non-tumor tissues and healthy controls in existing array datasets." (PMID 32171282, 2020).
cancer (93 papers, 2009 to 2026). A tumor composed of atypical neoplastic, often pleomorphic cells that invade other tissues. "We also demonstrated that the low level of elastin concentration induced some cancer-associated fibroblast (CAF) markers, including PDGFR-β, and fibrosis-related disease markers, including THY-1." (PMID 37848974, 2023). "Ferroptosis is a cell death method discovered when the small molecule substance elastin kills cancer cells containing the RAS mutation of the oncogene." (PMID 35242242, 2022). "The decline in levels of circulating estrogen associated with the natural aging process or with the oophorectomy, for cancer patients, causes a breakdown of the collagen and elastin fibers in the vagina." (PMID 28781968, 2017). "Additional experiments are required to better understand the overall effects of elastin degradation products on cancer-associated thrombosis." (PMID 26973522, 2016). "LOX family proteins are involved in the cross-linking of collagen and elastin, and play a key role in the remodeling of the extracellular matrix during development, injury, fibrosis, and the progression of cancer." (PMID 40786111, 2025). "Many of the most promising candidates for cancer detection, non‐invasively, remain at the proteomic (e.g., collagen and elastin etc.)and metabolomic (e.g., tryptophan, phenylalanine, proline, ceramides and fatty acid metabolites) levels." (PMID 40352638, 2025). "Elastin (ELN), a crucial member of the extracellular matrix family, has been documented to contribute to cancer cell invasion." (PMID 39749345, 2024). "Matrix metalloproteinase (MMP)-12 can degrade elastin as well as various extracellular matrix (ECM) components, which is associated with cancer progression." (PMID 38511770, 2024). "For the 20% elastin hydrogel, results showed that various biomarkers, including myofibroblast cell markers (α-SMA, THY-1) and cancer-associated markers (PDGF-β, S100A4), were involved in the FMT." (PMID 37848974, 2023). "These larger collagen and elastin fibrils, compared to adjacent tissue, have been observed to help facilitate cancer cell migration." (PMID 36765912, 2023). "Here, we demonstrated that elastin-likerecombinamer (ELR) hydrogels can be suitable biomaterials to developbreast cancer models." (PMID 36597885, 2023). "Various extracellular matrix (ECM)-related studies have reported the involvement of major structural protein such as collagen and elastin in aging as well as cancer." (PMID 36807774, 2023). "HGF, HMOX1, ELN, and GREM1 genes associate with stromal fibrosis and contribute to malignancy through the proliferation of cancer-associated fibroblasts (CAFs) in various kinds of cancers." (PMID 37240308, 2023). "An elastin stain to assess the pleural tissue is used for staging in pulmonary adenocarcinoma by examining the presence of cancer cells beyond the outer elastic layer or beyond this outer layer and onto the visceral pleura." (PMID 37894944, 2023). "It catalyzes ECM components such as type IV collagen, laminin, and elastin, and therefore, is thought to be involved in cancer invasion or metastasis." (PMID 37296952, 2023). "MMPs secreted by cancer cells and CAFs are capable of degrading collagen, elastin, and fibrin, thereby promoting cancer cell invasion and metastasis." (PMID 36422541, 2022). "MMP was regulated by the PI3K-AKT3 signaling pathway and was one of the most important proteases that degrade extracellular matrix proteins including collagen and elastin and also related to other severe diseases, such as cancer." (PMID 35935376, 2022). "Recently, it was shown that multivalent targeting of cancer (K562) cells by core-crosslinked elastin/resilin-like polypeptide micelles led to micelle to cell crosslinking." (PMID 34822576, 2021). "The main roles of LOXL1 include elastin homeostasis and matrix remodelling during injury and the development of fibrosis and cancer." (PMID 34440405, 2021).
cancer (continued). "One possible explanation is that cancer cells are able to synthesize elastin and express lysyl oxidase." (PMID 34827210, 2021). "Fibrinogen is one of many extracellular matrix (ECM) molecules such as collagen, elastin, and laminin that facilitate both normal and cancer cell migration, and regulate intercellular communication through growth factor sequestration." (PMID 36618440, 2021). "ELN recombinant protein increased cancer cell growth and reduced wound area after 6 h incubation compared to PBS controls." (PMID 32171282, 2020). "The interaction of cancer cells with elastin-derived peptides (EDP) induces mitogenic signals and a release of elastases that enhance further elastin degradation." (PMID 32351895, 2020). "ELN proteins had the high level in cancer cells after 48 h culture compared to normal colon epithelial cells." (PMID 32171282, 2020). "ELN protein was significantly increased in cancer cells after 48 h incubation compared to normal colon cells, although ELN protein was not changed at the early time point." (PMID 32171282, 2020). "EGCG prevents AG-9 stimulation and represents a molecule of choice to limit cancer progression in elastin-rich tissues." (PMID 33396696, 2020). "In summary, osteolytic cancer cells induce an accumulation of cells staining positive for αSMA, Elastin, Pdgfrb and Ly6a (Sca1)." (PMID 29988965, 2018). "Lysyl oxidase-like 2 (LOXL2) is a copper-dependent monoamine oxidase that contributes to the remodelling of the extracellular matrix (ECM) by cross linkage of collagen and elastin fibres and has emerged as a potential therapeutic target in cancer and fibrosis." (PMID 29953488, 2018). "During aging or pathophysiological conditions such as cancer progression, this insoluble polymer of tropoelastin undergoes an important degradation leading to the release of bioactive elastin-derived peptides (EDPs), named elastokines." (PMID 26973522, 2016). "Its degradation during cancer progression not only affects its mechanical properties but also generates elastin-derived peptides (EDP) that are actively involved in the development of cancer." (PMID 27148054, 2016). "These are secreted by tumors and are involved in cancer progression through their role in the post-translational oxidative deamination of peptidyl lysine residues on fibrous collagen and elastin." (PMID 26173873, 2015). "Reduced echogenicity of the skin may be a consequence of not only swelling, but also of an increased number of inflammatory or cancer cells or the destruction of elastin fibers." (PMID 40790900, 2025). "The reason for classifying components by their analogs is as follows: the monoterpenol group exhibits anti-inflammatory properties; the ester group promotes the synthesis of elastin, exhibiting anti-wrinkle activity; and the monoterpene group inhibits HepG2 cancer cells." (PMID 40573267, 2025). "The destruction of elastin promotes the development and progression of different pathological conditions, including chronic obstructive pulmonary disease, atherosclerosis, vascular aneurysms, and cancer." (PMID 37046716, 2023). "The destruction of elastin promotes the development and progression of pathological conditions, including chronic obstructive pulmonary disease, atherosclerosis, vascular aneurysms, and cancer." (PMID 37298452, 2023). "Thus, future research into the influence of elastin on cancer pathogenesis should include evaluations of matrix composition and relation to biomechanics." (PMID 37001705, 2023). "Decreased LOXL2, encoding lysyl oxidase-like 2 delta E13 (essential to connective tissue biogenesis, which catalyzes the first step in forming crosslinks in collagen and elastin), could contribute to the inhibition of cancer invasiveness." (PMID 37834191, 2023). "Indeed, MMPs can cleave collagen, elastin, and other extracellular matrix components favoring cancer cell spread." (PMID 35163058, 2022).
cancer (continued). "More importantly, our data raise the possibility that cancer cells can use the matrisome for disease expansion and could be effectively targeted by anti-collagen, anti-elastin, and/or anti-hyaluronic acid therapies." (PMID 35492318, 2022). "Elastin is a key protein in the ECM and has recently been implicated in cancer and EMT." (PMID 34359550, 2021). "Cancer-associated fibroblasts (CAFs) are abundant and extremely influential in this process and interact with cellular and matrix TME constituents such as endothelial and immune cells and collagens, fibronectin and elastin, respectively." (PMID 31992854, 2020). "We have also found increased ELN protein in cancer cells compared to normal colon epithelial cells." (PMID 32171282, 2020). "ELN protein was increased in cancer cells compared to normal colon epithelial cells." (PMID 32171282, 2020). "In addition, the level of VIM protein was also significantly increased in cancer cells after incubation with ELN protein and peptide compared to controls, indicating elastin proteins induced EMT in colon epithelial cancer cells." (PMID 32171282, 2020). "Elastin was reported to interact with invasive cancer cells through RPSA." (PMID 33396696, 2020). "MMPs include an arrangement of extracellular enzymes with proteolytic activities responsible for severing elastin, collagen, and fibrinogen to degrade the cellular matrix that is involved in multiple physiological processes, such as cancer metastasis, tissue remodeling and resorption." (PMID 31651935, 2019). "A follow-up study of 631 CRC resections found elastin-detected VI to be associated with a decrease in 5-year cancer-specific survival from 92 to 67% in node-negative disease (T1-4,N0) and from 79 to 42% in node positive disease (T1-4,N1/2)." (PMID 25601902, 2014). "However, elastin, under pathological circumstances, may undergo enzymatic degradation, yielding elastin peptide fragments, impacting the onset and progression of vascular diseases and cancer." (PMID 39399243, 2024). "We next determined whether ELN regulates cancer cell migration by performing a wound healing assay." (PMID 32171282, 2020). "In addition, through the generation of elastin fragments, NE may potently stimulate cancer cell invasiveness and angiogenesis." (PMID 26081156, 2015). "Furthermore, evidence suggests that VI assessed with an elastin stain may be a far better predictor of cancer survival than VI assessed by H&E alone." (PMID 25601902, 2014). "As CD26 expression can influence EMT induction in cancer, we analyzed the correlation of CD26 with the EMT phase markers E-cadherin, Vimentin, β-catenin, Elastin, Periostin, and Versican." (PMID 41426321, 2025). "The LOXL1 protein plays a key role in the maturation of elastin and the remodeling of the extracellular matrix (ECM) during tissue injury, fibrotic diseases, and the progression of malignant tumors." (PMID 40786111, 2025). "A cancer-adjacent blood vessel FOV is selected for verification because this FOV is rich in ECM including collagen and elastin." (PMID 38389847, 2024). "Genes LGALS8, PDE4DIP, RAD17, ELN, MUC4 and SEMA4D had a mid-range expression in both cancer types, while OPRM1 and ADRA1 were the least expressed, thereby corroborating the results from our box plot and survival analysis." (PMID 38544823, 2024). "Since elastin deposition influences TME remodeling and correlates to distal metastasis, elastin-targeting probes offer a promising cancer imaging and treatment approach." (PMID 39770505, 2024). "In lung and colon cancer, the degradation of the matrix and fragmentation of elastin was found mainly to occur at the invasive front, and the expression levels of MMP also correlated to the metastatic potential of these cancers." (PMID 37046716, 2023).